REN (renin)
Diseases named in the same sentence as REN in open-access papers (continued):
Sharing a sentence is not in itself a finding about the gene and the disease.
cardiac hypertrophy (continued). "The triple‐tg mice exhibited increased plasma renin activity, worsened cardiac hypertrophy, and higher mortality compared to CSQ‐tg mice." (PMID 32056390, 2020). "An increase in serum somatomedins levels was demonstrated in response to increased activity of the adrenergic system and the renin–angiotensin–aldosterone system, but in pathological heart hypertrophy." (PMID 31096682, 2019). "Retention of salt and water, characteristic for cirrhosis, induces the activation of the renin-angiotensin-aldosterone system, which further provokes cardiac remodeling-cardiac hypertrophy, intramyocardial fibrosis, and fibrosis of intramyocardial arteries." (PMID 31443575, 2019). "Previous studies reported that renin-angiotensin systems have an important role in hyperthyroidism-induced cardiac hypertrophy." (PMID 29881713, 2018). "AngII is the most important active ingredient in renin-angiotensin system and also an important humoral factor to regulate cardiac hypertrophy." (PMID 28164119, 2017). "First, it has been reported that SUA increases tumor necrosis factor-alpha, stimulates mitogen-activated protein kinases, and activates the renin-angiotensin system, all of which are known to promote cardiac hypertrophy." (PMID 27054027, 2016). "Active renin protein is produced and secreted from the liver, and the transgenic mice have increased circulating levels of Ang II and develop cardiac hypertrophy and hypertension." (PMID 26494430, 2015). "VDR but also CYP27B1 KO mice have high BP levels and cardiac hypertrophy due to increased activation of the renin-angiotensin system (RAS), and calcitriol treatment inhibits renin activation and decreases BP and cardiac hypertrophy in CYP27B1 KO mice." (PMID 25376735, 2014). "After 4 weeks, the increase in plasma renin activity, renal Ren1 expression, and cardiac hypertrophy were greater in db/db mice than in WT mice subjected to RAS." (PMID 24708836, 2014). "The activation of AT1 R through the renin-angiotensin system (RAS) plays an important role in the development of cardiac hypertrophy." (PMID 24028210, 2013). "The renin-angiotensin system has been classically shown to be a major regulator of pathologic cardiac hypertrophy." (PMID 23922949, 2013). "BNP shields the heart from negative effects caused by excessive strain by enhancing the excretion of sodium and causing diuresis, relaxing the smooth muscles of the blood vessels, suppressing the renin-angiotensin-aldosterone system, and cardiac remodelling through hypertrophy and fibrosis." (PMID 39897300, 2025). "Additionally, vitamin D influences cardiovascular health by regulating myocardial hypertrophy, arterial compliance, and the renin–angiotensin–aldosterone system." (PMID 40242208, 2025). "To date, the role of PAR-3 in hypertrophic or dilated cardiomyopathy has not been elucidated, despite evidence that inhibition of PAR-1 and PAR-2 — known interactors of PAR-3 — suppresses cardiac hypertrophy induced by pressure overload and in renin-overexpressing hypertensive mice." (PMID 41293419, 2025). "The elevation in cardiac weight, facilitated by an increase in fibroblasts, suggests that L-NAME could induce cardiac hypertrophy by activating the renin–angiotensin system." (PMID 38540933, 2024). "Overactivity of the renin–angiotensin–aldosterone system (RAAS)is the most important mechanism of myocardial hypertrophy as it can promotevasoconstriction, cardiac ischemia, myocardial apoptosis, and fibrosis, which arefundamental to ventricular tachyarrhythmias." (PMID 39077336, 2024). "Corin protein may be used to reduce cardiac hypertrophy and fibrosis, suppress the renin-angiotensin-aldosterone system, and improve cardiac function in HF." (PMID 37636304, 2023). "Furthermore, using lower alcohol concentration in our protocol, the Edn1 mRNA expression remained unchanged after PAEThe renin-angiotensin-aldosterone system (RAAS) contribution to cardiac hypertrophy is widely evidenced." (PMID 36829814, 2023).
cardiac hypertrophy (continued). "The beneficial reduction of cardiac hypertrophy and fibrosis observed in the current study may be mediated in part by inhibiting activation of the cardiac renin-angiotensin system post-MI." (PMID 32560137, 2020). "Additionally, we demonstrate that in the pathological highly relevant situation of an over-activated renin–angiotensin–aldosterone system (AII-induced heart hypertrophy), the increase in heart hypertrophy is associated with an increase in miR-221 and -222." (PMID 31312877, 2020). "Pathological cardiac hypertrophy could either result from pressure overload or due to abnormal activation of neurohormone system including sympathetic nervous system, renin-angiotensin system and endothelins." (PMID 28487655, 2017). "In recent years, a pivotal role of ACE2, ACE and their peptides were recognized during the inflammatory process such as glomerulonephritis, pulmonary hypertension, sepsis, lung injury, acute pancreatitis and also cardiac hypertrophy, while also being a key part of the renin–angiotensin system." (PMID 28336767, 2017). "Besides acting in the heart to contribute to ventricular hypertrophy, succinate can be a potent modulator of renin release." (PMID 26759054, 2016). "The authors confirmed the already accepted hypothesis that hypertrophy of the left ventricle and disturbances in its function lead to a stimulation of the renin-angiotensin system, adrenergic stimulation, and hyperinsulinemia." (PMID 24672357, 2014). "In addition, cardiac renin-angiotensin system activation (i.e. local) is important in the development of cardiac hypertrophy." (PMID 25171374, 2014). "We hypothesized that the renin-angiotensin system plays an important role in the development of cardiac hypertrophy and HF in this transgenic mouse model after the initiating stimulus of transfected constitutively active Gαq becomes undetectable." (PMID 25171374, 2014). "In addition, genetic disruption of the VDR resulted in overstimulation of the RAS with increased production of renin and angiotensin II, thereby leading to high blood pressure and cardiac hypertrophy." (PMID 22619734, 2012). "To examine whether overexpression of renin could compromise cardiac function we also measured some typical markers of cardiac hypertrophy such as brain natriuretic peptide (BNP) and the ratio of β/α myosine heavy chain (MHC)." (PMID 23300650, 2012). "Also enriched in CB-EPCs are HIF1α (hypoxia-inducible transcription factor 1 alpha) signaling, cardiac hypertrophy signaling, renin-angiotensin signaling and NFAT in cardiac hypertrophy pathways, reflecting the pro-angiogenic nature of CB-EPCs." (PMID 22943456, 2012). "However, blockade of gp91phox associated ROS production has no preventive effect on cardiac hypertrophy in Ang II over-production mice with transgenic overexpression of renin." (PMID 33664668, 2021). "It has been reported that α‐CGRP KO mice have increased activity of the circulating angiotensin‐renin system, and suggested that increased activity of the circulating angiotensin‐renin system might contribute in the further increase in cardiac hypertrophy in TAC α‐CGRP KO mice." (PMID 31724338, 2019). "Importantly, they proposed that ROS/NO balance may be a key player in controlling the TH-induced cardiac hypertrophy mediated by the renin-angiotensin system." (PMID 26146529, 2015). "Importantly, together these findings suggest that the cardiac renin-angiotensin system plays an important role in the development of cardiac hypertrophy, fibrosis and heart even if the initiating stimulus of cardiac Gαq activation does not result from AT1 receptor stimulation." (PMID 25171374, 2014). "Little seems to be known about the mechanism, if there is one, by which UA induces myocardial hypertrophy; possibilities may include activation of the renin-angiotensin system, enhanced production of reactive oxygen species, and upregulation of endothlin-1 expression." (PMID 24340056, 2013).
cardiac hypertrophy (continued). "It was found that in VDR knock-out mice, renin expression was increased and the RAAS was activated, leading to increased blood pressure and cardiac hypertrophy." (PMID 41048520, 2025). "Another important factor is renin–angiotensin–aldosterone system (RAAS) activation, potentially inducing myocardial fibrosis and hypertrophy." (PMID 37935940, 2024). "Over- activation of the renin–angiotensin–aldosterone system (RAAS) contributes to avid salt/water retention and cardiac hypertrophy in CHF." (PMID 37511227, 2023). "VDR-null mice exhibit dysregulation of the renin-angiotensin system (RAS), resulting in high blood pressure, cardiac hypertrophy, and overall elevated heart weight-to-body weight ratio." (PMID 35783863, 2022). "Activation of the renin‐angiotensin‐aldosterone system (RAAS) contributes to avid sodium retention, cardiac hypertrophy and oedema formation, including lung congestion." (PMID 33660945, 2021). "Angiotensin II (Ang II), a pivotal ingredient of the renin–angiotensin system (RAS), plays an important role in triggering hypertension and myocardial hypertrophy." (PMID 34194329, 2021). "It is also known that the renin-angiotensin system (RAS) plays an important role in cardiac remodeling and the beneficial effects of its inhibition on cardiac hypertrophy and dysfunction." (PMID 34007292, 2021). "The activation of the renin-angiotensin-aldosterone system (RAAS) and sympathetic nervous system leads to cardiac hypertrophy, which will result in ventricular remodeling and ultimately decompensation." (PMID 29849724, 2018). "The CSQ-tg mice treated with 300 mg/kg, the highest dose tested, of TAK-272 showed significantly reduced plasma renin activity (PRA), cardiac hypertrophy, and lung congestion." (PMID 30092100, 2018). "Our results showed that TAK-272 is an orally active and persistent renin inhibitor, which reduced the mortality of CSQ-tg mice and conferred protection against cardiac hypertrophy and injury." (PMID 30092100, 2018). "Although there are many factors and regulators that affect myocardial hypertrophy, the renin-angiotensin (RAS) and its primary effector peptide, AngII, are involved in the pathophysiology of cardiac hypertrophy and failure." (PMID 28713489, 2017). "The EE and BF of U. wallichiana attenuated cardiac hypertrophy by decreasing SBP and HR and inhibiting plasma renin, ACE, Ang II and augmented plasma NO and cGMP concentration." (PMID 28066255, 2016). "Measurements of plasma or urine aldosterone, catecholamines, cortisol and renin levels were obtained under a regular diet to obtain further insight into the mechanisms of DBP elevation and cardiac hypertrophy." (PMID 27166674, 2016). "Angiotensin II (AngII) is the central product of the renin-angiotensin system (RAS) and this octapeptide contributes to the pathophysiology of cardiac hypertrophy and remodeling." (PMID 25739102, 2015). "It is well known that the renin-angiotensin system, which increases the level of DAG, plays a critical role in the development of cardiac hypertrophy and HF." (PMID 25171374, 2014). "Renin–angiotensin-aldosterone system (RAAS) inhibitors are thought to be capable of reducing the left ventricular afterload in AS patients, thereby alleviating myocardial hypertrophy and fibrosis." (PMID 40269687, 2025). "Induces diuresis, natriuresis, and extracellular volume reduction, also potentiates the effects of renin-angiotensin-aldosterone system (RAAS) blockade on reducing pathological fibrosis and myocardial hypertrophy and improving cardiac function by blocking AngII receptors." (PMID 41586197, 2025). "The renin-angiotensin-aldosterone system (RAAS) has emerged as a significant pathway in cardiovascular physiology, although its multifactorial nature complicates efforts to isolate its specific contributions to cardiac hypertrophy." (PMID 41468376, 2025).
cardiac hypertrophy (continued). "Renin–angiotensin system (RAS) activation and increased angiotensin II (Ang II) expression can lead to left ventricular abnormalities, such as cardiac hypertrophy and fibrosis and expansion of cardiomyocyte extracellular matrix, contributing to cardiac dysfunction in CKD." (PMID 40225592, 2025). "It is a natural hormone with biological activities such as vasodilation, natriuresis, lowering blood pressure, inhibiting renin and aldosterone secretion, reducing sympathetic nervous system (SNS) tension, anti-myocardial fibrosis, and anti-myocardial hypertrophy." (PMID 39114359, 2024). "Given the direct deleterious effects of renin–angiotensin system activation on the myocardium in AS, ACEI may moderate myocardial hypertrophy and fibrosis and may have a beneficial effect on left ventricular remodeling in patients with severe AS." (PMID 33847680, 2021). "Possible mechanisms include irbesartan inhibiting the renin–angiotensin–aldosterone system (RAAS), reducing the level of AngII and blocking the binding of AngII to AT1R to improve the metabolism of myocardial fibroblasts and reduce myocardial hypertrophy." (PMID 33879070, 2021). "Treatment with captopril reduced cardiac hypertrophy in VDR knockout mice, suggesting that calcitriol may function as an endocrine suppressor of renin biosynthesis." (PMID 22619734, 2012). "Clinical studies revealed that patients with LV hypertrophy are associated with a higher incidence of congestive heart failure and sudden cardiac death compared with those without hypertrophy, and the renin–angiotensin system is known to play a key role in cardiac hypertrophy and heart failure (HF)." (PMID 38397106, 2024). "However, plasma renin in these mice remained elevated for 28 days after aortic transverse constriction, which indicates activation of the renin–angiotensin–aldosterone system (RAAS), an inducer of cardiac hypertrophy and fibrosis." (PMID 35207615, 2022). "The CFs derived exosomes upregulated the expression of renin, angiotensinogen, AT1R, and AT2R while downregulated expression of angiotensin-converting enzyme 2 and increased production of Ang II in cultured cardiomyocytes thus overall exacerbated Ang II-induced cardiac hypertrophy." (PMID 34869682, 2021). "Crude extract of Anogeissus acuminata decreased physical parameter ratios, lowered the plasma renin and plasma angiotensin II levels and increased nitrite/nitrate (NO) and cGMP plasma concentration levels against the ISO groups, showing the cardioprotective effects against cardiac hypertrophy." (PMID 32751601, 2020).
Hyperglycemia (163 papers, 2009 to 2025). An increased concentration of glucose in the blood. "A previously unpublished study revealed that microcurrent effectively lowered blood pressure by reducing liver fat metabolism caused by hyperglycemia and renin levels." (PMID 38553592, 2024). "Scorpion venom causes hyperglycaemia via different mechanisms such as massive catecholamine release, glucagon release, and glucocorticoid release, affecting renin–angiotensin–aldosterone system, causing hyperinsulinemia and cytokines release, etc.." (PMID 37624261, 2023). "Hyperglycemia causes an increased activity of the renin-angiotensin-aldosterone system on the local level, and it is well acknowledged that aldosterone causes proliferation of the smooth muscle and increases collagen synthesis in the vessel wall." (PMID 36330203, 2022). "Hyperglycemia has been linked to an increase in plasma renin activity with RAS activation, which is known to impair insulin signaling." (PMID 33120966, 2020). "Hyperglycemia causes a local increase in blood pressure due to the activation of the renin-angiotensin system (RAS)." (PMID 26798569, 2015). "Hyperglycemia and activation of the renin-angiotensin system are associated with oxidative stress, hypoxia, and endoplasmic reticulum stress, consequently triggering apoptosis of the renal tubular cells and epithelial–mesenchymal transition (EMT) during renal tubulointerstitial injury." (PMID 39940240, 2025). "In addition to its well-known metabolic assaults on the kidneys, hyperglycemia causes dysfunctional autoregulation in glomeruli by stimulating the intra-renal renin-angiotensin aldosterone axis, leading to activation of local AGII production." (PMID 26114547, 2015). "Hyperglycemia is associated with increased risk of all-site cancer that may be mediated through activation of the renin-angiotensin-system (RAS) and 3-hydroxy-3-methyl-glutaryl-coenzyme-A-reductase (HMGCR) pathways." (PMID 24886453, 2014). "Hyperglycemia increases myocardial production of angiotensin II and the renin-angiotensin system was associated with hypertrophy of cardiomyocyte and increase formation of glucose-derived advanced glycation end products, which contribute to myocardial stiffness." (PMID 23593350, 2013). "In addition, hyperglycemia causes hemodynamic changes in the kidney, oxidative stress, inflammation, hypoxia and deregulation of the Renin-Angiotensin-Aldosterone system (RAAS), which causes adverse changes in the kidney vessels, such as thickening of the glomerular basement membrane." (PMID 37089474, 2023). "Increasing sympathetic activity upon awakening from naps, mainly prolonged naps, could results in disruption of the sympathovagal balance, activation of the renin-angiotensin system, which can minimize pancreatic beta-cell insulin secretion, insulin resistance and associated hyperglycemia." (PMID 33921201, 2021). "Moreover, there is an association of high HbA1 levels with hyperglycemia, dyslipidemia and hyperinsulinemia, which mediates vascular dysfunction, activation of the renin-angiotensin-aldosterone system, sympathetic nervous system, and possibly negative alterations in BP." (PMID 26759608, 2016). "Hyperglycemia-associated increased formation of intracellular advanced glycation end-products (AGEs) and activation of protein kinase C isoforms, systemic and glomerular hypertension, and activation of renin-angiotensin system (RAS) are major factors in the pathogenesis of DN." (PMID 26000608, 2015). "The pathophysiology of DKD is complex, involving multiple pathways such as hyperglycemia, hemodynamic abnormalities, chronic inflammation, oxidative stress, and activation of the renin–angiotensin–aldosterone system (RAAS)." (PMID 40977986, 2025).